IDO1 (indoleamine 2,3-dioxygenase 1)
Diseases named in the same sentence as IDO1 in open-access papers (continued):
Sharing a sentence is not in itself a finding about the gene and the disease.
brain injury (1 paper, 2020). Acute and chronic (see also brain INJURIES, CHRONIC) injuries to the brain, including the cerebral hemispheres, CEREBELLUM, and brain STEM. "Although further studies are warranted, all data here might highlight a new and effective entry point for the prevention of ischemic brain injury by targeting IDO1+ pDCs." (PMID 32076400, 2020).
breast ductal carcinoma (1 paper, 2023). "The tumoral expression of CD274, TNFAIP3, IFNG and IDO1 in biopsy of breast ductal carcinoma was confirmed at the protein level via immunohistochemistry imaging." (PMID 38201582, 2023). "At the protein level, via immunohistochemistry, a weak expression of CD274 and moderate expression of ferroptosis drivers (IFNG, TNFAIP3 and IDO1) were observed in biopsy of ductal breast carcinoma." (PMID 38201582, 2023).
Breast invasive carcinoma (1 paper, 2018). "These positive correlations, in particular for IDO1 (p-value<0.01), were also confirmed with the data of The Cancer Genome Atlas Breast invasive carcinoma project (data not shown)." (PMID 29320557, 2018).
chordoma (1 paper, 2021). Chordomas are rare malignant tumors arising from embryonic remnants of the notochord in axial skeleton. "Notably, we also disclosed that B7H3, IDO-1 and Galetin-9 showed limited coexpression with each other or with PD-L1, suggesting an independent biological function of these proteins in chordoma, similar to previous observations." (PMID 35145510, 2021).
Cluster headache (1 paper, 2020). A type of headache characterized by repeated attacks of unilateral pain lasting 15 to 180 minutes and associated with local autonomic signs. "The IDO-1, IDO-2, and KMO enzymes and the kynurenine metabolite have been shown to be involved in the pathogenesis of neuropathic pain and other painful conditions (migraine, cluster headache, etc.)as well as depressive behavior." (PMID 32842609, 2020).
colorectal adenoma (1 paper, 2012). An adenoma that arises from the colon or rectum. "In contrast, colorectal adenomas, dysplastic precursor lesions of CRC, show comparable IDO1 immunoreactivity as normal colonic mucosa (no staining or weak staining, unpublished results)." (PMID 22108515, 2012).
complex regional pain syndrome (1 paper, 2020). A chronic pain syndrome characterized by a disproportionate spontaneous or stimulus-induced pain, accompanied by a variably mixed myriad of autonomic and motor disorders including symptoms such as swelling, allodynia, skin blood supply and trophic disturbances. "As a result, the KYN/TRP ratio is a well-established marker for IDO1 and inflammatory activation, with an elevated ratio observed in both chronic lower back pain and complex regional pain syndrome." (PMID 32973438, 2020).
craniopharyngioma (1 paper, 2024). A benign, partly cystic, epithelial tumor of the sellar region, presumably derived from Rathke pouch epithelium. "With the recent advances in precision medicine, some potential targets such as IL-6, PD1/PD-L1, MEK, IDO-1, and others have been identified for the treatment of craniopharyngioma." (PMID 39050573, 2024).
cystic kidney disease (1 paper, 2023). A congenital or acquired kidney disorder characterized by the presence of renal cysts. "However, at 6 months of age Pkd1RC/RC;Ido1–/– mice presented with decreased cystic kidney disease compared with Pkd1RC/RC;Ido1+/+ mice, independent of sex." (PMID 36422996, 2023).
diabetic nephropathy (1 paper, 2023). "Recently, researchers used microarray data for the first time for immune cell infiltration analysis to identify IDO1 as a diagnostic and prognostic biomarker for diabetic nephropathy (DN)." (PMID 37509627, 2023).
dysgerminoma (1 paper, 2025). A malignant germ cell tumor characterized by the presence of a monotonous primitive germ cell population. "When we compared the normalized counts of these immune checkpoints across the pediatric GCT subtypes, we found that dysgerminoma showed significantly higher expression of IDO1 and CTLA4 than the control group." (PMID 40621458, 2025). "In dysgerminomas, targeting IDO1 and CTLA4 could enhance T cell-mediated anti-tumor responses." (PMID 40621458, 2025). "Dysgerminomas exhibited an immune-active profile with elevated levels of T cells, CD8+ T cells, and cytotoxic cells, alongside upregulation of immune checkpoints CTLA4, TIGIT, and IDO1, suggesting potential responsiveness to checkpoint inhibitors." (PMID 40621458, 2025). "TIGIT, IDO1, CTLA4, and PDCD1 were specifically upregulated in dysgerminomas." (PMID 40621458, 2025).
Ebola virus disease (1 paper, 2024). "Additionally, previous drug discovery work for Ebola virus disease therapeutics has suggested IDO1, which is expressed by macrophages and modulates T cell activity, as a potential drug target." (PMID 39635525, 2024).
endometrial adenocarcinoma (1 paper, 2024). "IFN-γ treatment induced IDO1 in Ishikawa endometrial adenocarcinoma cells." (PMID 38540186, 2024).
endometrioid tumor (1 paper, 2024). A benign, borderline, or malignant epithelial tumor of the female reproductive system characterized by the presence of glands and/or cysts lined by neoplastic cells that resemble endometrial cells. "PD-L1 and IDO1 were more prevalent in HGSC compared to LGSC, mucinous and clear cell tumors, and on a similar level as endometrioid tumors." (PMID 39026018, 2024). "In contrast, endometrioid tumors were indicated to have a stronger presence of Tregs (FOXP3 and CTLA-4), and tumor PD-L1 and IDO1 levels on par with HGSC." (PMID 39026018, 2024).
Epileptic spasm (1 paper, 2022). A sudden flexion, extension, or mixed extension-flexion of predominantly proximal and truncal muscles that is usually more sustained than a myoclonic movement but not as sustained as a tonic seizure. "We hypothesised that, as in the rodent model of epileptic spasms, there could be IDO1 activation due to inflammation." (PMID 36174397, 2022).
esophageal tumor (1 paper, 2020). "IDO-1, which induces tolerance to self-antigens via inhibition of T cell activation, exhibits a sevenfold higher expression in primary untreated esophageal tumor in comparison to healthy normal tissue, whereas it has a fourfold higher expression in NACT treated patients." (PMID 31960110, 2020).
Ewing sarcoma (1 paper, 2015). A small round cell tumor that lacks morphologic, immunohistochemical, and electron microscopic evidence of neuroectodermal differentiation. "In our Ewing sarcoma model, we observed modulation of immunosuppressive indoleamine 2,3-dioxygenase 1 (IDO) expression by stimulation of the CD137/4-1BBL system." (PMID 26579494, 2015).
fibrosarcoma (1 paper, 2020). A malignant mesenchymal fibroblastic neoplasm affecting the soft tissue and bone. "Here, by using a preclinical model of fibrosarcoma, we evaluated the benefit on in vitro and in vivo anti-tumor response of IDO1 blockade through a pharmacological approach using GDC-0919 alone or in combination with an immune checkpoint blocker." (PMID 32194552, 2020).
hantavirus infection (1 paper, 2023). "The expression of IDO1 and its secretion during hantavirus infection is novel as it has only been previously reported during human cases of nephropathia epidemica (NE), a milder form of HFRS caused by Puumala orthohantavirus infections." (PMID 37766212, 2023).
hemophilia (1 paper, 2020). Hemophilia is a genetic disorder characterized by spontaneous hemorrhage or prolonged bleeding due to factor VIII or IX deficiency. "The potential role of regulators of peripheral tolerance has been recently explored in hemophilia, with a specific focus on two immunoregulatory enzymes: heme oxygenase-1 (HO-1) and indoleamine 2,3 dioxygenase (IDO; IDO-1)." (PMID 32351505, 2020).
HER2 positive breast carcinoma (1 paper, 2024). A biologic subset of breast carcinoma defined by high expression of HER2, GRB7, and TRAP100, and by lack of expression of estrogen receptor (ER). "It has been shown that PDPN-positive CAF can promote resistance to trastuzumab in Her2-positive breast cancer by secreting the immunosuppressive factors indoleamine 2,3-dioxygenase 1 (IDO1) as well as tryptophan 2,3-dioxygenase 2 (TDO2)." (PMID 38728370, 2024).
hypopharyngeal carcinoma (1 paper, 2025). Carcinoma, predominantly squamous cell, arising from the epithelial cells of the hypopharynx. "When looking at the different anatomical locations of the HNSCC, the majority of hypopharyngeal carcinoma showed a high expression of IDO1, as well as p16-negative and p16-positive oropharyngeal squamous cell carcinoma (OPSCC)." (PMID 40332319, 2025).
immunotoxicity (1 paper, 2020). "Tα1 resorted to IDO1 to limit the ICI-mediated immunotoxicity at the mucosal site." (PMID 32817121, 2020).
intestinal cancer (1 paper, 2020). "The presence of IDO1+ Paneth cells in intestinal cancers might provide an explanation for these observations." (PMID 32444775, 2020).
invasive carcinoma (1 paper, 2024). A carcinoma that is not confined to the epithelium, and has spread to the surrounding stroma. "Other differentially expressed transcripts include S100A7, LCN2, CXCL14, and CD207 (decreasing expression from premalignant lesions to invasive carcinoma), as well as IDO1, IL6, IL8, THBS1, and FN1 (increasing expression from premalignant lesions to invasive carcinoma)." (PMID 38706595, 2024).
ischemic disease (1 paper, 2022). Lack of blood supply to an area of the body, resulting in impairment of tissue oxygenation. "We found that OGD may affect the IDO1/KYN metabolic pathway through IL11, thereby affecting fibroblast senescence and collagen expression, which may provide an effective basis for the treatment of cellular senescence caused by ischemic disease." (PMID 36292942, 2022).
Kidney Cyst (1 paper, 2023). Abnormal fluid filled sac within the kidney, either acquired or congenital. "Further, we found IDO1 to be expressed in primary epithelial cells derived from individual kidney cysts of ADPKD patients." (PMID 36422996, 2023).
kidney transplant (1 paper, 2023). A surgical procedure in which one or both kidneys from a donor are implanted into a recipient. "Our comprehensive analysis of biopsy samples from a substantial cohort of kidney transplant recipients demonstrates a compelling association between IDO1 expression in tubules and rejection incidence, particularly in T-cell mediated rejection (TCMR) and antibody-mediated rejection (AMR)." (PMID 38137602, 2023). "These associations suggest that IDO1 may play a protective role in kidney transplant rejection." (PMID 38137602, 2023). "Our study further delved into the intricate interplay between IDO1 expression and T-cell mediated rejection (TCMR) in kidney transplant recipients." (PMID 38137602, 2023).
laryngeal squamous cell carcinoma (1 paper, 2018). A squamous cell carcinoma that arises from the larynx. "Indoleamine 2,3-dioxygenase 1 (IDO1) is a catabolizing enzyme that induces immune tolerance by suppressing T-cells and has been found to be associated with poor outcome in laryngeal squamous cell carcinoma." (PMID 30211111, 2018).
leiomyoma (1 paper, 2022). A well-circumscribed benign smooth muscle neoplasm characterized by the presence of spindle cells with cigar-shaped nuclei, interlacing fascicles, and a whorled pattern. "The mRNA levels of other tryptophan metabolizing enzymes, IDO1 and IDO2, were low and not significantly different, suggesting that TDO2 is the key enzyme responsible for reduced tryptophan levels in mut-MED12 leiomyoma." (PMID 35064560, 2022).
liver dysfunction (1 paper, 2021). "Moreover, a study reported TDO activity was also inhibited strongly by CCl4 treatment, thus the incorporation of IDO1, IDO2 and TDO into liver dysfunction will be crucial revelation enlightenment." (PMID 34869457, 2021).
lymphadenopathies (1 paper, 2023). "Our results further adds important clues to the complex immune response orchestrated by the lymphoid system in benign lymphadenopathies and can be of guidance for future studies on inflammatory and malignant conditions when IDO1 and PD-L2 are studied." (PMID 36830609, 2023). "Therefore, IDO1 has been proposed as a possible target for treatment in AD, but expression of IDO1 in AD patients with benign lymphadenopathies has not been investigated." (PMID 36830609, 2023). "However, to imunohistochemically stain for IDO1 and PD-L2 in benign lymphadenopathies might not capture the complex inflammatory process in patients with AD." (PMID 36830609, 2023).
mastocytosis (1 paper, 2023). A clonal myeloproliferative neoplasm characterized by the proliferation and accumulation of neoplastic mast cells in one or multiple organs or organ systems. "Mastocytosis patients display significantly higher levels of indoleamine-2,3-dioxygenase-1 (IDO1) activity, leading to hyperactivation of the N-methyl-D-aspartate receptor." (PMID 36831056, 2023). "As cannabidiol (CBD) is known to inhibit IDO1's enzymatic activity, we hypothesized that pharmaceutical-grade CBD is an effective treatment for mastocytosis-associated pain." (PMID 36831056, 2023).
Merkel cell carcinoma (1 paper, 2023). "In a study of Merkel cell carcinoma (MCC), MCC cells with lower IDO1 expression but a tumour microenvironment with lower TDO2 and AhR expression had a longer overall survival rate." (PMID 38062922, 2023).
mucinous tumors (1 paper, 2024). "For example, mucinous tumors displayed a more active immune response compared to the other low-grade carcinomas, with relatively higher levels of CD8 cytotoxic T cells and immune activation marker VISTA, while lower in immune suppressive markers (IDO1, FOXP3, CTLA4)." (PMID 39026018, 2024).
mucosal melanoma (1 paper, 2020). A melanoma that arises from a mucosal site. "The association between PARP1 and IDO1 and their combined adverse prognostic role raise the potential of combined therapy in mucosal melanoma." (PMID 32380691, 2020). "The association between PARP1 and IDO1 and their combined negative prognostic role raise the potential of combined therapy in mucosal melanoma." (PMID 32380691, 2020).
muscle atrophy (1 paper, 2025). The loss of muscle tissue due to inactivity or disease. "Though none of the IDO-1 inhibitors have been tested in a GC-treated model directly, increasing muscle tryptophan and preventing KYN accumulation through IDO-1 inactivation may lead to positive outcomes in various cases of muscle atrophy, including GC-related muscle atrophy." (PMID 40806744, 2025).
Mycobacterium infection (1 paper, 2022). Infections with bacteria of the genus Mycobacterium. "IDO activity is regulated by Mycobacterium infection and host gene polymorphisms, especially in IDO1 and IDO2, and the balance of their expression in TB." (PMID 35045867, 2022).
myeloid leukemia (1 paper, 2012). A clonal proliferation of myeloid cells and their precursors in the bone marrow, peripheral blood, and spleen. "IFN-γ is a prototypical IDO1-inducing cytokine in solid tumor cell lines, but not in cells of either lymphoid or myeloid origin, such as MM and myeloid leukemia cells." (PMID 23232072, 2012).
neurofibroma (1 paper, 2023). An intraneural or extraneural neoplasm arising from nerve tissues and neural sheaths. "While upregulation of PD-L1 in pNFs and MPNSTs has been recently noted, to our knowledge, the current study is the first to observe an overexpression of (IDO1) in neurofibromas." (PMID 37817770, 2023). "Notably, we identified tumor-associated IDO1+/CD274+ (PD-L1)+ dendritic cells, which represent the first such observation in any NF1 animal model and suggest the role of the upregulation of immune checkpoints in mature neurofibromas." (PMID 37817770, 2023).
ocular infection (1 paper, 2012). "We also identified other genes, including IDO1 and BAMBI, that may influence the RPE and therefore outer blood-retinal barrier integrity during ocular infection and inflammation, or are associated with degeneration, as seen for example in aging." (PMID 22509103, 2012).
oral cancer (1 paper, 2024). "One study reported that high IDO1 expression has prognostic potential, while another study indicated that IDO1 could be used as a prognostic marker only in the early stages of oral cancer." (PMID 38736462, 2024).
oral mucositis (1 paper, 2023). Inflammation of the mucous membranes of any of the structures in the mouth. "In this study, the upregulation of IDO1 by administered melatonin may have been related to the mechanism of suppression of radiation-induced oral mucositis." (PMID 37681910, 2023).
ovarian adenocarcinoma (1 paper, 2023). An adenocarcinoma that arises from the ovary. "Previous studies showed that higher IDO1 expression in high‐grade ovarian adenocarcinoma is associated with better prognosis, including better overall and progression‐free survival rates." (PMID 38062922, 2023).
pancreatitis (1 paper, 2022). Inflammation of the pancreas. "They showed that administration of complete Freund adjuvant, a mixture of lipids composed of Mycobacterium tuberculosis extracts known to activate IDO1 expression, induced severe pancreatitis in IDO1-KO mice in comparison with wild-type controls." (PMID 36188218, 2022).
papillary thyroid cancer (1 paper, 2022). "Conversely, in papillary thyroid cancer most checkpoint molecules, including LAG-3, PD-1, inducible T cell COStimulator (ICOS), and indoleamine 2,3-Dioxygenase 1 (IDO1), were significantly decreased compared with healthy thyroid tissues." (PMID 36077354, 2022).
parasite (1 paper, 2019). "Catabolic fate of tryptophan and regulation of functional IDO1 are also important to determine the fate of parasite infection." (PMID 30770800, 2019).
peripheral nerve injury (1 paper, 2022). Injury to a peripheral nerve. "Similarly to what we found for the case of IDO1, HAAO was also identified in DCs that accumulate in the DRLs after peripheral nerve injury." (PMID 36227694, 2022). "Furthermore, these results also indicate that IDO1-derived kynurenines have no role in microglial cell activation in the dorsal horn of the spinal cord after peripheral nerve injury." (PMID 36227694, 2022).
postweaning multisystemic wasting syndrome (1 paper, 2022). Pig disease caused by porcine circovirus type 2 (PCV2). "An up-regulation of TIM3 and IDO1 has been described in the context of PRRSV- and CSFV-infected pigs, respectively, whereas LAG3 was reported to play a limited role during the pathogenesis of postweaning multisystemic wasting syndrome." (PMID 36713151, 2022).
prostate tumors (1 paper, 2024). "We identified the upregulation of immunomodulatory molecules, such as IDO1, TIM3, and CD274(PD-L1), in both prostate tumors expressing higher levels of MHC-I and -II genes." (PMID 38704603, 2024).
Protein-losing enteropathy (1 paper, 2019). Abnormal loss of protein from the digestive tract related to excessive leakage of plasma proteins into the lumen of the gastrointestinal tract. "Post hoc analysis of IDO-1 mRNA expression in the duodenal mucosa of dogs with protein-losing enteropathy (PLE), chronic enteropathy (CE), and healthy Beagle control dogs using RNA in situ hybridization." (PMID 31181125, 2019).
Q fever (1 paper, 2023). A bacterial infection caused by Coxiella burnetii. "Notably, the effect of deletion of Acod1 on C. burnetii replication was much stronger than the impact of deficiencies of several other IFNγ‐induced antimicrobial defense mechanisms (NOS2, IDO1/2, GBPs), thus establishing ACOD1 as a major protective determinant in the host defense against Q fever." (PMID 36479617, 2023).
retinitis (1 paper, 2019). Inflammation of the retina. "Of course, it is difficult (virtually impossible) to determine the impact of an additional IDO1 deficiency in hRPE during hCMV retinitis." (PMID 30781494, 2019).